ENSG00000259060 (novel protein)
Gene: Protein-coding gene on chromosome 14 (20,582,892 to 20,609,795, reverse strand). Ensembl gene ENSG00000259060.
Genetic constraint (gnomAD): Loss-of-function variants: 7 observed, 5.04 expected, observed/expected ratio (o/e) 1.39, 90% interval 0.75 to 1.92. That is too few expected variants to judge how well the gene tolerates losing a copy. Missense variants: 114 observed, 119.66 expected, observed/expected ratio (o/e) 0.95, 90% interval 0.82 to 1.11. Synonymous variants: 41 observed, 40.14 expected, observed/expected ratio (o/e) 1.02, 90% interval 0.8 to 1.33.